CTLA4 (cytotoxic T-lymphocyte associated protein 4)
Diseases named in the same sentence as CTLA4 in open-access papers (continued):
Sharing a sentence is not in itself a finding about the gene and the disease.
tumor (continued). "ICIs involves mainly CTLA-4, PD-1, PD-L1 or LAG-3 blocking agents that reactivates the immune system against tumour cells." (PMID 38322766, 2024). "Surprisingly, the analysis of CD8+ T cell subtypes revealed a significant increase in intra-tumor NK1.1+ CD8+ T cell infiltration after anti-CTLA4 Ab and combination therapy, unveiling a novel anti-CTLA4 Ab-dependent anti-tumor mechanism." (PMID 38398223, 2024). "Results from a panel of in vivo and ex vivo 3D tumor models imply that, beyond driving CD8+ T cells into T-cell exhaustion, a major role of PD-1 and CTLA-4 is in limiting the CXCR3-based self-feeding mechanism of T cell potentiation." (PMID 39474427, 2024). "The other targeting strategy involves the blockade of immune checkpoint inhibitors (e.g., PD-1/PD-L1, CTLA-4, TIM-3, and LAG-3; see Section 5.2) to modulate the immune response towards tumor cells and increase the probability of tumor cell death." (PMID 38258110, 2024). "T cell exhaustion occurs due to increased inhibitory signals from molecules such as PD-1, Tim-3, LAG-3, VISTA, CTLA-4, and TIGIT, affecting both tumor cells and T lymphocytes." (PMID 39684867, 2024). "A particularly enlightening scenario that unveils the intricate connection between autoimmunity and anti-tumor responses is observed with the use of immune checkpoint inhibitors (ICI) targeting PD-1 and CTLA-4 inhibitory molecules." (PMID 38318190, 2024). "butyrate restrains anti-CTLA-4-induced up-regulation of CD80/CD86 on dendritic cells and ICOS on T cells, accumulation of tumor-specific T cells and memory T cells." (PMID 39351241, 2024). "Mechanistically, the study demonstrates that CLF enhances the efficacy of dual anti-PD-1 + CTLA-4 ICB by promoting a specialized CD8+ T cell population with memory potential, improving tumor eradication across various murine models." (PMID 39156659, 2024). "The therapeutic efficacy of anti-PD1, CTLA4 treatment alone, or in combination was assessed using the YTN16 peritoneal dissemination tumor model." (PMID 38805119, 2024). "Significant growth delay was observed in the tumor growth for both the anti-CD47 Ab group and the anti-CTLA4 Ab group compared to the control group." (PMID 38398223, 2024). "At the same time, lycorine hydrochloride treatment alone and in combination with anti-mouse CTLA-4 was also able to significantly increase the ratio of cytotoxic CD8+ T cells, signifying a notable enhancement in tumor immunity." (PMID 39245716, 2024). "Compared with other regions, the local TME in the invasion zone is highly immunosuppressive, characterized by increased expression of immune checkpoint genes, such as CTLA-4, CD96, and TIGIT, creating a favorable environment for tumor progression." (PMID 39085965, 2024). "Due to the limited studies on CTLA-4 inhibitor monotherapy for advanced HCC, its anti-tumor activity and safety cannot be accurately assessed at this time, and more studies are expected to follow to validate it further." (PMID 39185414, 2024). "Regulatory T cells (Tregs, CD4_cluster2) with FOXP3, CTLA4, ICOS, and BATF expression were also abundant, which has been demonstrated as tumor-specific alterations in the tissue microenvironment." (PMID 39514276, 2024). "Various studies have suggested that the markers of T‐cell exhaustion, such as CTLA‐4, BTLA, LAG‐3, 2B4, TIM‐3, CD160, and PD‐1, induce the functionally impaired state and thereby suppress the proliferation of the exhausted T cells in tumor tissues." (PMID 38204220, 2024). "Effector Tregs are the predominant subtype of Tregs in tumor tissues and are characterized by coexpression of the transcription factor FOXP3 and the transmembrane protein CTLA4." (PMID 39227950, 2024). "We also predicted the response of AML patients to the existing ICIs targeting PD-1 and CTLA-4 using the online TIDE tool, which integrates both intrinsic tumor cell characteristics and the tumor microenvironment to assess the response to immunotherapy." (PMID 38807380, 2024).
tumor (continued). "Despite the significant efficacy demonstrated by CTLA-4 and PD-1/PD-L1 inhibitors, the overall effectiveness of current ICI therapy remains modest due to the complex tumor microenvironment and tumor heterogeneity." (PMID 39839672, 2024). "We further showed that both CpG-Stat3 siRNA and CTLA4 antibody inhibit STAT3 in B malignant cells, leading to tumor cell apoptosis and/or proliferation inhibition." (PMID 39618825, 2024). "Nevertheless, the correlation found between several immune cell populations, and in particular between FoxP3+ and CTLA-4+ cells, suggests a potential role of immune cells in canine splenic HSA where mechanisms of tumor evasion are activated." (PMID 38672372, 2024). "It seems that there is a preferential binding of CTLA-4 to CD80 or CD86, outcompeting CD28 and therefore interrupting T-cell activation, thus mediating immune evasion and escape mechanisms of tumor cells." (PMID 39409094, 2024). "Reduction of tumor growth was observed in either AUY-922 or anti-CTLA monotherapy, but a further decrease of tumor growth was observed in the AUY-922 and anti-CTLA4 combinational treatment group." (PMID 38762492, 2024). "In cytotoxic T cells, CTLA-4 competitively shatters the bond between ligands and its co-receptor CD28, thereby destroying its anti-tumor function." (PMID 39013849, 2024). "In summary, our study validates the binding of AYA22T-R2-13 to CTLA-4, thereby amplifying CTL-mediated tumor lysis." (PMID 38473398, 2024). "With a preference for tumor localization, MEDI5752 demonstrates superior in vivo activity compared to anti-PD-1 and anti-CTLA4 antibody combinations." (PMID 38475778, 2024). "We found that the immune checkpoint molecule CTLA-4, which is currently widely used in clinical applications, was significantly overexpressed in the high-risk group, indicating that the high-risk group may have a suppressive TME that is more unfavorable for tumor immunity." (PMID 39091494, 2024). "Immune checkpoint inhibitors (such as anti-CTLA-4, anti-PD1 and anti-PD-L1) are monoclonal antibodies which work by activating immune responses, thus halting tumor evasion." (PMID 39595113, 2024). "Most clinical studies failed to elicit a strong antitumor immune response and subsequent systemic tumor regression after radiation therapy (RT), even in combination with the immune checkpoint inhibitors (ICI) anti-CTLA4 or anti-PD1." (PMID 38500667, 2024). "Mice were subcutaneously inoculated with 1 × 106 B16F10 tumor cells and randomized into the following systemic treatment groups: vehicle, anti-CTLA-4, TPPU, or a combination of anti-CTLA-4 and TPPU." (PMID 38330013, 2024). "Although the mechanism is not fully understood, CTLA-4 inhibition may lower the priming threshold for new T cell activation and has been shown to increase the diversity of the T-cell receptor repertoire, potentially enabling a response to a greater range of tumour neoantigens." (PMID 38811992, 2024). "Since NK cells can express CTLA4 and CD2548,49, we utilized anti-OX40 Abs, which efficiently deleted the FoxP3+ CD4 T cells within the tumor while leaving NK cells intact." (PMID 38267402, 2024). "We first compared therapy responses by re-inoculating each tumor cell line into naïve mice and administering combination therapy including gemcitabine, nab-paclitaxel, agonistic anti-CD40 Ab, anti-CTLA-4 Ab, and anti-PD-1 Ab (GAFCP)." (PMID 38378697, 2024). "The common immune checkpoints include CTLA-4, LAG-3 and PD-1, all of which are widely distributed in solid tumors and have a critical function in the tumor microenvironment (TME)." (PMID 38571495, 2024). "In this work, we undertake a comprehensive molecular exploration of tumor intrinsic and immune microenvironmental features to further unravel resistance to PD1 and CTLA4 blockade." (PMID 38594286, 2024).
tumor (continued). "It simultaneously blocks CTLA-4 with CD80/85 and PD-L1 with programmed cell death-1 (PD-1) to inhibit immunosuppressive effects, which restores T-cell effector immune response to tumor and deletes Treg cells (suppress tumor immunity) in tumor microenvironment." (PMID 38310192, 2024). "We found that the activities of target genes regulated by NR3C1, STAT1, and STAT3 were higher in tumor tissues, implying that NR3C1, STAT1, and STAT3 played critical regulatory roles for the development of CTLA4+ T cell subsets." (PMID 38604154, 2024). "Among 14 cases showing positivity for CTLA-4 in ICs, a total of six cases (five PTC and one ATC) showed co-expression for PD-L1 in tumour cells." (PMID 39286684, 2024). "These agents’ anti-tumor activities have been demonstrated in Phase I, II, and III studies, with CTLA-4 and PD-L1 standing out as the primary molecules targeted by immunotherapy modalities results." (PMID 37614091, 2024). "First, a subcutaneous transplantation tumor model of NSCLC cells in mice was established, and this model was treated with a combination of Abs targeting CD47 and CTLA4." (PMID 38398223, 2024). "Tremelimumab is another humanized IgG2 monoclonal antibody against CTLA-4, which binds to CTLA-4 and blocks its interaction with ligands CD80 and CD86, thereby enhancing T cell response to tumor cells." (PMID 38177102, 2024). "PD-1/L-1, CTLA-4, and CD80/CD86 interactions are two crucial immune checkpoint pathways in the tumor microenvironment (TME)." (PMID 38791528, 2024). "Since little activation of CD8+ T or increase in intra-tumor infiltration by anti-CTLA-4 Ab was observed in our model, it is unlikely that Treg function was altered by anti-CTLA-4 Ab." (PMID 39106430, 2024). "Except for insufficient CD8+ T infiltration, T cell exhaustion featured by upregulating inhibitory receptors like PD-1, CTLA-4 and TIM-3 also paved the way for the immune escape of tumor cell." (PMID 39538125, 2024). "The bindings of PD-1 and CTLA-4, expressed on activated T cells, to their ligands on tumor cells (PD-L1) or antigen-presenting cells (APCs) (CD80/CD86) restrain the anti-tumor T cell activities." (PMID 38280003, 2024). "Indeed, blocking other inhibitory receptors on ILC1s for example cytotoxic T-lymphocyte-associated protein 4 (CTLA-4), T cell Ig and ITIM domain (TIGIT) and T cell immunoglobulin and mucin domain-containing protein 3 (TIM3) may similarly enhance ILC1 anti-tumour activity." (PMID 38745765, 2024). "Important checkpoints in CRC are lymphocyte-activation gene 3 (LAG3), CTLA4, T-cell immunoglobulin and mucin-domain containing-3 (TIM-3) and PDL1, which control tumor growth and progression." (PMID 39080202, 2024). "On the basis of several preclinical murine models showing improved tumour control after CTLA-4 blockade, anti-CTLA-4 human mAbs were constructed." (PMID 36980527, 2023). "A combination treatment involving lipofermata and a CTLA4 antibody in TC-1 and LLC tumor-bearing mice demonstrated a synergistic tumor-suppressive effect compared to treatment with either agent alone." (PMID 37700339, 2023). "Monotherapy with anti-CAIX, combination therapy with two immune checkpoint inhibitors (anti-PD-1 and anti-CTLA-4), as well as combination therapy with anti-CAIX and anti-PD-1 resulted in a short decrease in tumor volume, followed by renewed growth." (PMID 37373220, 2023). "In the field of tumor immunotherapy research, the six immune checkpoints PDCD1, CD274, CTLA-4, LAG-3, TIGIT, and HAVCR2 can inhibit the proliferation, activation and effector functions of T cells, and maintain the immune homeostasis in the body." (PMID 37810780, 2023). "The main groups of Mabs in SCC therapy are Mabs targeting EGFR, HER2, HGF, and VEGF, alongside checkpoint inhibitors (including Mabs to PD‐1, CTLA4, and NKG2A) and tumor targeting Mabs." (PMID 37042307, 2023).
tumor (continued). "We also compared the differences in expression levels of TEX marker genes (HAVCR2, TIGIT, CTLA4, LAG3, and PD1) and the putative tumor stem cell marker genes (CD44 and PROM1) between high and low TEXSRGs-score groups in clinical tumor samples using qRT-PCR." (PMID 37957420, 2023). "Tumor-reactive CD8+ T cells generally showed a methylation pattern like exhausted cells, as exhausted signature genes (PDCD1 and CTLA4) were found to be demethylated the same as how in naïve T cells they were found to be hypermethylated." (PMID 36672677, 2023). "ICI drugs act by blocking inhibitory receptors, cytotoxic T lymphocyte antigen-4 (CTLA-4), and programmed death-1 (PD-1) on T lymphocytes and their interaction with their corresponding ligands (CD80/86 and PD-L1/-L2, respectively) on tumor cells." (PMID 37887315, 2023). "The addition of anti-CTLA-4 antibody treatment to PDT treatment with the particle-induced increased amounts of CD8+ T cells and reduced the numbers of Tregs in tumor infiltrates." (PMID 36839652, 2023). "CTLA-4 inhibitors thus function by inhibiting CTLA-4, allowing CD28-B7 crosslinking and activation of T cells for its activity against tumor cells." (PMID 36776886, 2023). "Gene expression analysis in dMMR/MSI-H CRC demonstrated high levels of the immune checkpoints CTLA-4, PD-1, PD-L1, LAG-3, and IDO in different compartments, such as tumor-infiltrating lymphocytes, tumor stroma, and the invasive front of the tumor." (PMID 37894457, 2023). "Notably, while IL-6 blockade promoted anti-tumor immunity in combination with anti-CTLA4, it ameliorated pathology driven by autoreactive Th17 responses, suggesting that IL-6/IL6R blockade may have the added benefit of attenuating immune-related adverse events." (PMID 36599350, 2023). "Findings from other studies highlighted the central role of the tumor microenvironment (TME) in nivolumab, pembrolizumab, and anti-CTLA-4 response." (PMID 37055532, 2023). "CSCs express CD47, CTLA4, PD-L1, TIM-3 and LAG3, which promote immune evasion in the malignant environment and maintain tumor survival." (PMID 36810098, 2023). "The commonly used immunosuppressant targets PD-1/PD-L1 and CTLA-4 can inhibit the killing effect of CTL on tumor cells, while neoantigen vaccines can activate immune cells in the tumor microenvironment." (PMID 37415744, 2023). "Treatment with the combination of N1, FSL-1, R848, and anti-CTLA4 or the combination of N1, FSL-1, anti-CTLA4, and SX882 induced 4T1 tumor regressions with 20% of treated 4T1 tumor-bearing mice achieving a complete response and remaining in remission." (PMID 37190294, 2023). "Another study demonstrated that 5-aza-2’-deoxycytidine significantly enhanced the tumor cell-killing effects of MAGE-As co-antigen peptide-specific CTLs and anti-CTLA-4 monoclonal antibody in BC cells." (PMID 38268926, 2023). "Studies have shown that the expression of CTLA-4 in CD8+ and CD4+ T cells isolated from HCC tissues is significantly higher than that in tumor-free tissues or blood." (PMID 37304265, 2023). "We observed that anti-VISTA 13F3 antibody induced potent tumor growth inhibition (TGI) when used in combination with anti-mPD-L1 (B16-F10 model) or anti-mPD-L1 and CTLA-4 (CT26 model)." (PMID 38152397, 2023). "As a result of the interaction between T cell’s CTLA-4 and B7 expressed in APC, the immune response to tumor cell is suppressed, and CTLA-4 also functions as a checkpoint in the immune process." (PMID 36674491, 2023). "In TIGIT+ Treg cells, the expression level of many immunosuppressing marker genes, including Foxp3, Helios, neuropilin-1, CTLA-4, PD-1 and LAG-3, was upregulated, which inhibited the tumor killing function of T cells." (PMID 38110467, 2023). "The anti-CTLA4-TGFβ-R2 molecule is more effective than ipilimumab (an anti-CTLA-4 antibody), at inhibiting tumor progression and decreasing tumor-infiltrating Treg cells." (PMID 37007004, 2023).
tumor (continued). "PD1 (PDCD1), PD-L1 (CD274), CTLA-4, and TIM-3 (HAVCR2) are important immune checkpoints responsible for tumor immune escape." (PMID 36714030, 2023). "We discuss the therapeutic potential of ILCs beyond the classical PD-1 and CTLA-4 regulatory molecules, exploring other possibilities to manipulate ILC effector function to further impede tumor growth and quench disease progression." (PMID 37514187, 2023). "To evaluate the contribution of either CD4+ or CD8+ T cells in the anti–PD-1/CTLA-4 combination, we tested the in vivo effects of CD4+ and/or CD8+ T cell depletion on syngeneic tumor growth." (PMID 37449205, 2023). "Tumor infiltrating CD8 T cells and CAR-T cells express inhibitory checkpoints, such as PD-1 and CTLA-4, which can suppress T cell activity upon binding their ligand expressed on cancer cells and tumor-infiltrating myeloid cells." (PMID 36831591, 2023). "Most immune checkpoints, including CTLA-4, PD-1, and PD-L1 with antibodies approved by the Food and Drug Administration (FDA), are expressed in exhausted T cells (Texh) that have encountered tumor antigens." (PMID 39872303, 2023). "Three days after tumor implantation, mice were randomized into four different treatment controls: vehicle control, ICT (anti-PD-1 and anti-CTLA-4), CBLB502 treatment, and CBLB502 in combination with ICT treatment at the indicated dose and delivery method." (PMID 36635337, 2023). "For example, RT increases diffusion of immune cells into the tumor microenvironment allowing anti-tumor effects, while simultaneous anti-PD-L1, anti-PD1 and anti-CTLA-4 therapy can offset the immunosuppressive consequences induced by RT." (PMID 37554167, 2023). "Our analysis of immune cell subtypes and immune checkpoint gene expression revealed that the PTMC-Inf tumor shares the same characteristics (more infiltrating CD4 + and CD8 + T cells, and high expression of PDL1, PDCD1, and CTLA4)." (PMID 36941725, 2023). "C5aR1 showed a negative correlation with the immunological status of TME and a positive correlation with most immune checkpoints in GC, including PD-L1, CTLA-4, LAG-3, and PD-1, which suppress the effector function of T cells and impede anti-tumor immunity." (PMID 36508191, 2023). "However, high TMB and increased PD-L1 expression together represent key characteristics of an immunogenic tumor that has developed PD-1 axis mediated adaptive immune resistance, which may be used to select patients for treatment with anti-PD-1 or anti-CTLA-4 ICIs." (PMID 37377970, 2023). "Diverse studies revealed that the expression of immune-checkpoints (i.e., CTLA-4, PD-1 and PD-L1) and cytolytic activity markers (i.e., GZMA and PFR1) are important to determine the functional status of local anti-tumor immune response." (PMID 37260772, 2023). "Stimulation of anti-tumor immunity via immune checkpoint inhibitors (ICI) such as anti-PD-1/PD-L1 and anti-CTLA-4 has proven successful for several tumor types, but results in breast cancer are still modest." (PMID 37450065, 2023). "In terms of immune checkpoints, the expressions of CTLA4, CD276, CD47 and TNFRSF25 were significantly higher in “stiff tumor”." (PMID 37179366, 2023). "Correlations between the upregulation of CD80, CD86, and CD28 have been found in OSCC, and the lack of change in CD28 and PD-1 transcripts in our tumor samples, which might have been associated with the complexity in CTLA4 abundancy, requires further stratification." (PMID 36983005, 2023). "Flow cytometric analysis later examined the proportion of BCSCs, the proportion of CTLA4+ T cells and the cytotoxicity of CD8+ T cells in the tumour tissues." (PMID 37838657, 2023). "Combined ICI and MWA share similar trends: anti-CTLA-4 co-administered with MWA and GM-CSF contribute to 90% secondary tumor rejection in Hepa 1-6 model mice." (PMID 37251920, 2023).